ENSG00000200235
Synonyms: LOC124900208
Gene: Small nucleolar RNA gene on chromosome 5 (140,579,667 to 140,579,792, forward strand). Ensembl gene ENSG00000200235.
Gene Ontology:
Biological process: RNA processing
Cellular component: nucleolus
Homologues: Paralogues in human: SNORA27 (90% identical).